HSPA14 (heat shock protein family A (Hsp70) member 14)
Description:
Component of the ribosome-associated complex (RAC), a complex involved in folding or maintaining nascent polypeptides in a folding-competent state. In the RAC complex, binds to the nascent polypeptide chain, while DNAJC2 stimulates its ATPase activity.
Synonyms: HSP70L1; HSP70-4
Tractability: Antibody: its Gene Ontology location is reachable by antibodies, with medium confidence. PROTAC: ubiquitination databases record sites on it; its protein half-life has been measured.
Gene: Protein-coding gene on chromosome 10 (14,838,306 to 14,871,741, forward strand). Ensembl gene ENSG00000187522.
Subcellular location: Cytoplasm, cytosol
Pathways (Reactome):
Cellular responses to stimuli: Regulation of HSF1-mediated heat shock response
Gene Ontology:
Molecular function: protein binding; ATP hydrolysis activity; heat shock protein binding; protein folding chaperone; ATP binding
Biological process: 'de novo' cotranslational protein folding; protein folding; protein refolding
Cellular component: cytosol; membrane; protein folding chaperone complex; ribosome; nucleus; plasma membrane
Genetic constraint (gnomAD): Loss-of-function variants: 11 observed, 23.88 expected, observed/expected ratio (o/e) 0.46, 90% interval 0.29 to 0.76. The upper end of that interval is the gene's LOEUF score, 0.76, which puts it in group 3 of 6, group 1 being the genes least tolerant of losing a copy. Missense variants: 313 observed, 335.39 expected, observed/expected ratio (o/e) 0.93, 90% interval 0.85 to 1.02. Synonymous variants: 123 observed, 129.66 expected, observed/expected ratio (o/e) 0.95, 90% interval 0.82 to 1.1.
Homologues: Orthologues: chimpanzee HSPA14 (99% identical), macaque HSPA14 (98% identical), dog HSPA14 (95% identical), rabbit HSPA14 (95% identical), pig HSPA14 (94% identical), guinea pig HSPA14 (93% identical), mouse Hspa14 (91% identical), rat Hspa14 (90% identical), tropical clawed frog hspa14 (76% identical), zebrafish hspa14 (70% identical), Caenorhabditis elegans hsp-70 (35% identical), Caenorhabditis elegans F44E5.4 (34% identical), and 2 more. Paralogues in human: HSPA2 (36% identical), HSPA8 (36% identical), HSPA1A (35% identical), HSPA1B (35% identical), HSPA1L (35% identical), HSPA6 (35% identical), HSPA5 (35% identical), HSPA9 (31% identical), HSPA4 (28% identical), HSPA4L (26% identical), HYOU1 (26% identical), HSPH1 (25% identical), and 1 more.
Diseases named in the same sentence as HSPA14 in open-access papers:
HSPA14 is named in the same sentence as 16 diseases in open-access papers, as found by Europe PMC text mining. Sharing a sentence is not in itself a finding about the gene and the disease. The quoted sentences say what the papers report.
breast carcinoma (2 papers, 2021 to 2024). "There are data that suggest the acquisition of radioresistance by human breast cancer cells is accompanied by the enhancement of HSPA14 expression; however, a causal link between the intratumoral HSPA14 level and tumor radiation response has not been yet established." (PMID 34943954, 2021).
cervical cancer (2 papers, 2019 to 2021). A primary or metastatic malignant neoplasm involving the cervix. "While some studies have shown that HSPA14 (HSP70L1) is associated with the overall survival and recurrence of cervical cancer, siRNA-mediated inhibition of HSPA14 can reduce the migration, invasion, and transformation activity of NBS-1 overexpressed cells." (PMID 34059060, 2021). "Four characteristic genes, HSPA14, SDHAF2, CAMKK2 and TM9SF1, that can be used as prognostic markers for cervical cancer were selected." (PMID 31744495, 2019).
lung carcinoma (2 papers, 2020 to 2021). "We experimentally characterized the dual function of two genes, DNAJC9 and HSPA14, in lung cancer cells." (PMID 33225964, 2020). "Among these, we experimentally validated the dual functions of DNAJC9 and HSPA14 in a lung cancer cell line." (PMID 33225964, 2020). "HSPA14 and HSPA4L were mainly expressed in lung cancer and large intestine cancer cell lines." (PMID 34712697, 2021).
celiac disease (1 paper, 2016). An autoimmune genetic disorder with an unknown pattern of inheritance that primarily affects the digestive tract. "HSP90AA1, MKKS, EZR, HSPA14, APOB and CAD are proteins that involved in protein networks of celiac disease and have been determined as seeds." (PMID 27895852, 2016).
hepatoma (1 paper, 2021). "Univariate and multivariate analyses showed that HSPA4 and HSPA14 could be independent risk factors for the prognosis of hepatocellular carcinoma patients." (PMID 34059060, 2021). "Cell experiments have also confirmed that reducing HSPA4 and HSPA14 expressions can inhibit the invasion, metastasis, and proliferation of hepatocellular carcinoma cells." (PMID 34059060, 2021). "For instance, HSPA4 and HSPA14 can be novel therapeutic targets and prognostic biomarkers for hepatocellular carcinoma." (PMID 34059060, 2021). "However, the mechanism of HSPA4 and HSPA14 effect on the occurrence and development of hepatocellular carcinoma is unknown and should be studied." (PMID 34059060, 2021). "The scratch spacing significantly decreased in the NC group after 48 h, but there was no significant change in HSPA4 and HSPA14 knockdown groups, indicating that the migration ability of hepatoma cells decreased, similar to the migration and invasion assays." (PMID 34059060, 2021).
HIV-1 infection (1 paper, 2023). The type species of lentivirus and the etiologic agent of acquired immunodeficiency syndrome (AIDS). "Kinetic expression profile studies for HSPA14 were performed following HIV-1 infection in Jurkat cells, CEM cells and TZM-bl cells." (PMID 36845091, 2023). "We next examined HSPA14 expression levels during HIV-1 infection." (PMID 36845091, 2023). "HIV-1 infection resulted in down-modulation of HSPA14 mRNA and protein expression." (PMID 36845091, 2023). "Thus, this study aims to investigate the role of HSPA14 in HIV-1 infection." (PMID 36845091, 2023). "We found that the mRNA and protein levels of HSPA14 in the Jurkat, CEM and TZM-bl cells decreased gradually with increasing HIV-1 infection time." (PMID 36845091, 2023). "Finally, through the in vitro cell experiments, we found that the expression level of HSPA14 was inhibited after HIV-1 infection, HSPA14 also inhibited the replication level of the virus and may play a role similar to that of the viral replication inhibitor HspBP1." (PMID 36845091, 2023).
cancer (6 papers, 2013 to 2021). A tumor composed of atypical neoplastic, often pleomorphic cells that invade other tissues. "Besides, the high HSPA1A, HSPA1B, HSPA4, HSPA5, HSPA8, HSPA13, and HSPA14 expressions were inversely associated with the overall survival rate of patients, tumor grade, and cancer stage." (PMID 34059060, 2021). "In the HSP70 family, HSPA7 was positively enriched in 19 cancer types, while HSPA14 was negatively enriched in 19 cancer types." (PMID 33225964, 2020). "For example, DNAJC9 positively correlated with cell proliferation in 32 cancer types, and HSPA14 positively correlated with cell proliferation in 24 cancer types." (PMID 33225964, 2020). "The HSPA4/HSPA14 axis induces the migration, invasion, and transformation of cancer cells." (PMID 25379943, 2014). "Among these HSPs, DNAJC9 and HSPA14 are two top genes with striking dual functions in that they promoted cell proliferation but inhibited EMT in 18 and 17 cancer types, respectively (i.e., in LUAD)." (PMID 33225964, 2020).
tumor (6 papers, 2016 to 2023). "The high HSPA4 expression was associated with vascular invasion, while the high HSPA14 expression with the higher T stage of the tumor." (PMID 34059060, 2021). "HSPA4 and HSPA14 expressions were significantly associated with various tumor grades." (PMID 34059060, 2021). "The HSPA14 was one of overexpressed proteins in HCC tumour tissues." (PMID 27895852, 2016). "The Basal subtype showed the highest number of specific upregulated genes (DNAJC2, DNAJC6, HSPA5, HSPA14 and CRYAA), DNAJA3 and CCT2 were upregulated in Luminal B, and DNAJB3 was only upregulated in HER2 tumours." (PMID 29954368, 2018). "Therefore, the high HSPA4 and HSPA14 expressions are associated with tumor proliferation, invasion and metastasis, indicating that their high expressions could influence the prognosis of HCC patients by accelerating tumor proliferation, invasion, and metastasis of tumor." (PMID 34059060, 2021).
infection (1 paper, 2023). The state of being infected such as from the introduction of a foreign agent such as serum, vaccine, antigenic substance or organism. "Further verification with CD4+ T cells isolated from healthy human peripheral blood showed that the mRNA and protein levels of HSPA14 in the CD4+ T cells infected with HIV-1 pseudoviral particles also decreased with increasing infection time." (PMID 36845091, 2023). "Constructing HSPA14 overexpression or knockdown cells to detect intracellular HIV replication levels after in vitro infection." (PMID 36845091, 2023).
HSPA14 also shares sentences with these, for which no sentence is quoted: colon cancer (2 papers); COVID-19 (1); glioma (1); large intestine cancer (1); latent infections (1); liposarcoma (1); melanoma (1).